IFNG (interferon gamma)
Diseases named in the same sentence as IFNG in open-access papers (continued):
Sharing a sentence is not in itself a finding about the gene and the disease.
tumor (continued). "IFNγ and NF-κB induces iNOS expression in tumor cells and myeloid cells." (PMID 26497740, 2015). "In conclusion, the results of the present study revealed that elevated pre-operative serum HGF levels were indicative of invasive growth of tumor foci, categorized as IFNγ, and characterized by high-grade tumors with an unclear border between the tumor and the surrounding tissue." (PMID 25592281, 2015). "Finally, vaccination of mice with the Ad5-PK vector resulted in enhanced T-cell-mediated interferon gamma (IFN-γ) release in response to both mesothelin peptide and a tumor line expressing mesothelin." (PMID 25933160, 2015). "Interestingly, administration of a mixture of B. breve and B. longum to Tac mice resulted in improved tumor control and increased IFNγ levels in tumor-draining lymph nodes and spleen." (PMID 26689196, 2015). "To test whether there were antigen specific CD8+ IFNγ secreting T cells, analogous to those which would be critical for the generation of tumor immunity, we evaluated the cultures for expansion of influenza M1 specific dextramer positive cells." (PMID 25475068, 2014). "However, the combination of RT and anti-CTLA-4 induced significant tumor-specific IFNγ production (p < 0.005 versus all other groups), as expected given the therapeutic synergy we have previously shown with this combination." (PMID 25349699, 2014). "The cytokine type II interferon (IFNγ) can be used as a therapeutic agent as it exerts a variety of different anti-tumor effects, including inhibition of cancer cell proliferation, repression of tumor angiogenesis, and the induction of tumor cell apoptosis." (PMID 25428727, 2014). "Mechanistically, COX-2 expression blunted the interferon-gamma release of antigen-specific T cells exposed to their respective cellular targets, and increased the expression of interleukin-4 and indoleamine 2,3-dioxygenase by tumor cells." (PMID 25501829, 2014). "The secretion of IFNγ was stimulated to a low extent by treatment of the coculture with tremelimumab, recommend the use of the H-1PV/tremelimumab combination treatment to enhance tumor immunogenicity through both DC activation and CTLA-4 masking." (PMID 24822170, 2014). "In addition to the cytokines that are known to induce MDSC accumulation, we also found an increase in serum levels of IFNγ and IL-10 in several tumor models." (PMID 25401795, 2014). "Thus, these two therapeutics together complement each other, resulting in the massive infiltration of IFNγ-producing T cells into the tumor." (PMID 24416401, 2014). "To determine if blockade of CD1d in the context of radiotherapy and CD137 costimulation resulted in improved priming of anti-tumor CD8+ T cells in dLN of WT mice similar to that observed during anti-CTLA-4 blockade, we measured tumor antigen-specific production of IFNγ by dLN cells." (PMID 25349699, 2014). "We also explored the anti-tumor effects of IFNγ through the activation of the immune response." (PMID 25428727, 2014). "Activation as measured by the expression of CD25, CD69 or IFNγ can be achieved by Fc receptor cross-linking, exposure to NK-sensitive tumor cells, co-incubation with mature dendritic cells, in vivo infections with bacteria such as listeria monocytogenes, among others (and data not shown)." (PMID 25101668, 2014). "The intratumoral influx of CD8+ cells together with the locally increased production of IFNγ, the functional T-cell response against the tumor, and the protective immunity against tumor rechallenge, point towards an essential role of CD8+ T-cells during this treatment." (PMID 24866126, 2014). "Therefore, the anti-tumor effect of the combination therapy is at least partially dependent on IFNγ." (PMID 24416401, 2014).
tumor (continued). "However, although the combination treatment resulted in 60% of WT mice being tumor-free by day 20, tumors developed in all IFNγ KO mice treated with CY+1D11 by day 12 (p<0.05)." (PMID 24416401, 2014). "Among these cytokines, IFNγ has been recognized as its pivotal role in anti-tumor immunity by enhancing tumor immunogenicity for antigen presentation, inducing apoptosis in tumor cells, promoting T helper 1 (Th1) differentiation and augmenting cytotoxicity of CD8+ cytotoxic T lymphocytes (CTLs)." (PMID 24363024, 2014). "IFNγ is a cytokine with pleiotropic effects on tumour cells, which is also considered as a crucial mediator of effective antitumour immunity displaying direct impacts on tumour cells." (PMID 25071011, 2014). "Besides, IFNγ/TRAIL combination immunotherapy has been shown to synergistically induce tumor cell death." (PMID 25428727, 2014). "In the adaptive immune response against human cancer, CD8+ cytotoxic T lymphocytes (CTLs) have played one of the most important roles that attacking cancer cells by producing interferon gamma to induce apoptosis of tumor cells and macrophage tumor killing activity." (PMID 24743335, 2014). "Methylation-mediated IFNG decreases may benefit tumor survival and shift the balance of tumor immunity towards tumor progression." (PMID 24244422, 2013). "IFNγ has a myriad of functions in the immune system’s ability to control the growth of or eliminate tumors, notably the recruitment and activation of cells of the innate immune system and enhancing the production of anti-tumor chemokines." (PMID 26344346, 2013). "The HPV16-SLP vaccine was well tolerated and induced a broad IFNγ-associated T-cell response in patients with advanced or recurrent HPV16-induced gynecological carcinoma but neither induced tumor regression nor prevented progressive disease." (PMID 23557172, 2013). "Anti-tumor effector function of the aAPC-expanded TIL could be confirmed for this patient, as demonstrated by IFNγ secretion after co-culture with autologous tumor cells." (PMID 23402380, 2013). "Human tumor-infiltrating Th17 cells have been reported to produce high levels of TNFα and IFNγ." (PMID 24454480, 2013). "Although there is evidence suggesting a pro-tumor role for Th17 cells, accumulating data supports the notion that Th17 cells play an important anti-tumor role, particularly in the context of immune responses with combined Th1/Th17 properties and IFNγ production." (PMID 26344346, 2013). "When co-cultured with KIT+ tumor cells, both 1st and 2nd gen dTc proliferated and produced IFNγ." (PMID 23433424, 2013). "Mice treated with a vaccine targeting the H-2Db-restricted epitope of the Human Papilloma Virus 16 (HPV-16) E7 protein after C3 fibrosarcoma tumor implantation and exposed to ATRA displayed a 3 fold decrease in tumor growth and improved splenocyte IFNγ production." (PMID 24829747, 2013). "Host immune system activation by IFNG is crucial for an anti-tumor response." (PMID 24244422, 2013). "IFNG is inappropriately hyper-methylated in tumor-infiltrating lymphocytes in colon cancer, which may represent a form of tumor-induced immunosuppression." (PMID 23720660, 2013). "Furthermore, research demonstrated enhanced exosomal HSP72, induced by IFNγ stimulation of tumor cells, resulted in the up-regulation of CD83 and potentiation of IL-12 production in DCs." (PMID 24376443, 2013). "The pathway is enriched with correlating genes from normal and tumor data as well as with predicted miRNAs that could play a crucial role in modulating interferon gamma (IFNG) signaling regulation." (PMID 23325622, 2013). "Therefore, elucidating the molecular mechanisms of IFNG in tumorigenesis is critical to have a more clear understanding of tumor pathogenesis." (PMID 24244422, 2013). "Interestingly, the IL-21 aAPC expanded CD8+ T cells demonstrated superior functional tumor recognition, with significantly higher IFNγ release levels than the CD8+ T cells expanded by IL-2 and IL-15 aAPC." (PMID 23402380, 2013).
tumor (continued). "Regression is characterised by significant increase in MHC class I and class II expression on the surface of the CTVT cells (MHC expression on 31% of cells), an infiltration of lymphocytes into the tumour mass and an increase in interferon-gamma (IFN-γ) production." (PMID 23200636, 2013). "Indeed, on a per cell basis, TILs in the tumor of PPI-treated mice produced more IFNγ than TILs from mice treated with vehicle." (PMID 24062984, 2013). "IFNγ may also promote tumoricidal activity in other immune cell populations within the tumor microenvironment." (PMID 23060881, 2012). "In our study, we considered the influnce of inflammatory microenvironment on MSCs, and used IFNγ and TNFα stimulating MSCs to imitate the tumor inflammatory microenvironment, and then took the conditioned medium to treat different HCC cells, which was different from the conditions mentioned aboved." (PMID 22952657, 2012). "In response to IFNγ, dendritic cells and tumor cells may produce IDO, whose enzymatic activity leads to the degradation of tryptophan and the production of toxic catabolites such as kynurenine and quinolinate." (PMID 22924042, 2012). "Given that CD8+ T cell-derived TNFα and IFNγ can sensitize tumor stroma and mediate bystander tumor eradication, we speculate that polyfunctional CD4+ effector T cells have the same effect because these cells can produce these two cytokines simultaneously." (PMID 22400040, 2012). "Importantly, activated CD4 T cells are a major source of IFNγ, an effector cytokine with potent tumor regressing activity via inhibition of tumor-induced angiogenesis or activation of tumor-infiltrating macrophages." (PMID 22400038, 2012). "Therefore, IFNγ can negatively affect both oncolytic virus replication and tumor-specific immunity at several levels." (PMID 22924042, 2012). "IFNγ presents a potential impediment to virus replication in tumor cells in vivo." (PMID 22924042, 2012). "IFNγ-producing T cells play a crucial role in the elimination of tumor cells." (PMID 22642942, 2012). "IFNγ responds against intracellular pathogens and tumour control." (PMID 22321936, 2012). "CD4+ and CD8+ T cells also produced IFNγ upon re-stimulation with NT2.5 tumor lysate-pulsed DCs." (PMID 22397502, 2012). "However, high but not low avidity T cells transferred into tolerant mice are able to reach a level of activation required to produce IFNγ and mediate tumor lysis." (PMID 22359647, 2012). "Besides its immunomodulatory effects, IFNγ has an influence on proliferation and induces apoptosis in vitro in many primary tumor cells and established tumor cell lines." (PMID 22919516, 2012). "We speculate that iNOS activity of cells derived from tumor-bearing mice may be boosted by T cell-produced IFNγ both in vivo and in vitro, which might explain this discrepancy." (PMID 23234398, 2012). "In pilot studies, we found that DSL-6A/C1 cells can attract local fibroblasts to the tumor, where they may exert effects of tumor stroma cells and are possibly targeted by IFNγ." (PMID 21310022, 2011). "We hypothesize that IFNγ inhibits tumor progression through two mechanisms, reduction of fibrogenesis and antiproliferative effects on the tumor cells." (PMID 21310022, 2011). "Explanted tumour cell retained their sensitivity to the IFNγ treatment." (PMID 22015556, 2011). "Finally, spleen and tumor derived myeloid cells from MT/ret mice inhibit efficiently antigen specific T cell proliferation and IFNγ secretion." (PMID 21633700, 2011). "We showed recently that tumor skewed IL10-producing M2 macrophages can fully revert to IL12-producing M1 macrophages following interaction with CD4+ Th1 cells or with CD40-L-expressing cells in the presence of IFNγ." (PMID 22176642, 2011).
tumor (continued). "Conditioning with cyclophosphamide injected one day before cryoablation led to increased IFNγ production of tumor-antigen specific CD4+ T cells in a mouse colon cancer model as detected in intracellular cytokine staining, enhanced survival and even some complete remission." (PMID 22242035, 2011). "Myeloid cells from tumor and spleen of MT/ret mice inhibit T cell proliferation and IFNγ secretion." (PMID 21633700, 2011). "Explanted tumour cells remained fully sensitive to the IFNγ treatment." (PMID 22015556, 2011). "In the coculture model, IFNγ increased expression of IL-1β, which might favor the development of a pro-inflammatory microenvironment in the tumor." (PMID 21310022, 2011). "However, in mc-CMV-IFNγ treatment groups, mice bearing the CNE-2 tumor had much higher expression level of IFNγ in their livers than those bearing the C666-1 tumor." (PMID 21573215, 2011). "The mathematical model not only reproduced the experimental data, but also underscored the conclusions drawn from the experiments by indicating that a maximum of 1/500 of total STAT1 is located as phosphorylated STAT1 in the nucleus upon IFNγ treatment of the tumor cells." (PMID 21310022, 2011). "We have assessed the level of the MHC class I and selected immunoactive molecules expression on the TC-1/A9 tumour cells excised from the tumour-bearing animals and cultured ex vivo and compared these levels with the expression level on the cells treated in vitro with the epigenetic agents or IFNγ." (PMID 22015556, 2011). "These cells have several characteristics of tumor associated macrophages (TAMs), including impaired activation of NF-κB, lack of nitric oxide production in response to LPS/IFNγ (not shown) and high constitutive STAT1 signaling." (PMID 20661477, 2010). "Indeed, the authors showed that TRAIL is, at least in part, responsible for NK cell mediated, IFNγ dependent, mechanism of tumor elimination." (PMID 20661477, 2010). "Tumor-specific T cells induced by the HLA matched allogeneic pDC were highly functional as demonstrated by the capacity of tetramer+ T cells to secrete IFNγ and express CD107 upon specific restimulation, and their strong antigen and HLA-A*0201-specific cytotoxicity." (PMID 20454561, 2010). "A key cytokine in tumor-suppressive networks is IFN-gamma (IFNγ)." (PMID 19503789, 2009). "Finally, 4-1BB stimulation modifies the distribution pattern of tumor-specific T cells in vivo, in a manner that is largely dependent on IFNγ." (PMID 19759901, 2009). "Therefore, adenovirus-mediated intratumoral delivery of the IFNγ gene is a promising approach because it achieves high and sustained local IFNγ expression in the tumor." (PMID 19216804, 2009). "Ad-IFNγ DNA was detected in tumor, blood, and parenchymal organs." (PMID 19216804, 2009). "However, TNFα production stimulated by ligation with antibody-coated tumor cells was significantly inhibited in IFNγ primed macrophages treated with Ly294002 indicating that the PtdIns 3-kinase/Akt pathway is involved in FcγR-mediated TNFα production." (PMID 19148288, 2009). "To evaluate the dynamic expression in vivo of the transgene from the recombinant human IFNγ adenovirus, we used ELISA to test the levels of IFNγ in samples collected from tumor, heart, liver, spleen, lung, kidney, brain, and blood on days 1, 2, 3, 5, 7, 14, and 21 post-injection of Ad-IFNγ." (PMID 19216804, 2009). "On day 14 and 21, only a minimal amount of IFNγ remained in the tumor." (PMID 19216804, 2009). "IFNγ was detected in tumor and parenchymal organs, while IFNγ was undetectable in blood." (PMID 19216804, 2009). "In previous studies with pcDNA3.1-Mage-b vaccination, we found that the number of CD8 T cells significantly increased in the 4T1 tumours of Mage-b vaccinated mice compared with the control groups, despite very poor Mage-b-specific immune responses (IFNγ production) in the draining LNs." (PMID 18728665, 2008).
tumor (continued). "IFNG has important immunoregulatory functions such as antiviral and anti-tumor activity, and as an activator of macrophages, yet its functions in T-cell activation remains unknown." (PMID 18485203, 2008). "Furthermore, the cytokines IL-2, IL-4, TNFα and IFNγ have been shown to inhibit tumor-induced angiogenesis in some animal models by inhibition of tumor stroma formation." (PMID 19578507, 2008). "Moreover, treatment of tumor bearing mice with Ad-Flt3L and Ad-TK induced a robust increase in the total number of tumor responsive T cells that secreted IFNγ when co-incubated with BMDC loaded with GL26 cell extracts (p<0.001)." (PMID 18431473, 2008). "Cell surface marker analysis, cytotoxic activities against autologous tumor cells and interferon-gamma examination of ascites suggested the possibility that these effects were mediated by immunological responses of activated killer cells and dendritic cells infused intraperitoneally." (PMID 19055844, 2008). "Interestingly, a much smaller percentage (approximately 40% reduction) of Tregs was observed in tumours excised from IFNγ−/− mice compared to those from WT mice." (PMID 17565340, 2007). "IFNγ is often used as an indicator of effector T cell functional capacity, and it had previously been shown in another tumor model that while tumor-antigen specific effector T cells traffic systemically after adoptive transfer, they produced IFNγ only within the tumor site." (PMID 17786193, 2007). "However, tumor cells are able to escape from the control of this cytokine in the early tumor stages; this is probably due to a decreased expression of IFNγ, or also to an alteration of either its receptors or some transduction elements." (PMID 17697357, 2007). "To gain an insight into the mechanism of tumour rejection in Treg-depleted animals, we determined whether treatment of IFNγ−/− mice with CD25-specific mAbs offered protection against the development of MCA-induced tumours." (PMID 17565340, 2007). "Alternatively, the impact of Treg activity on tumour development may differ between IFNγ−/− and wild-type mice." (PMID 17565340, 2007). "Interestingly and in contrast to our observations in wild-type mice, tumours appeared slightly yet significantly earlier in IFNγ−/− mice receiving CD25-specific mAbs compared to those that received control mAbs." (PMID 17565340, 2007). "IFNγ plays an important role in controlling development of MCA-induced tumours." (PMID 17565340, 2007). "Likewise, the T cell line primed with RCC-53-loaded RNA was activated specifically to secrete IFNγ using either RCC-53 tumor cells or autologous LCLs pulsed with RCC-53-derived total RNA." (PMID 16045799, 2005). "Only co-culture with RCC-26 cells, but not with autologous LCL-26, the normal kidney cell line (NKC-26), or the HLA-A*0201-matched tumor cell line RCC-53 induced IFNγ-release, indicating that only RCC-26 cells provided the specific ligand for TIL-26 activation." (PMID 16045799, 2005). "To study mechanisms providing tumour resistance to endogenous IFNγ, we analysed primary TGCT and two human TGCT cell lines (NTERA and NCCIT) for the expression of IFNγ receptor and for the level of phosphorylation of the signal transducer and activator of transcription (STAT)-1." (PMID 12942126, 2003). "For an autocrine effect, IFNγ must be secreted by tumour cells." (PMID 12942126, 2003). "Moreover, corroborating our ex vivo data, we found significantly increased activation of T cells from clusters relative to T cell singlets, as judged by upregulation of CD137, PD-1, CD39 and increased PD-L1 expression by tumour cells (indicative of IFNγ secretion by active neighbouring T cells)." (PMID 41261135, 2026). "Our results from healthy tissue (GTEx) and tumor (TCGA) analysis demonstrated a significant negative correlation between AR activity and the three IFNγ-associated signature scores in normal tissue and tumors, suggesting conserved AR-regulated biology irrespective of malignancy status." (PMID 41486951, 2026).